UTP18 (UTP18 small subunit processome component)
Description:
Part of the small subunit (SSU) processome, first precursor of the small eukaryotic ribosomal subunit. During the assembly of the SSU processome in the nucleolus, many ribosome biogenesis factors, an RNA chaperone and ribosomal proteins associate with the nascent pre-rRNA and work in concert to generate RNA folding, modifications, rearrangements and cleavage as well as targeted degradation of pre-ribosomal RNA by the RNA exosome. Involved in nucleolar processing of pre-18S ribosomal RNA.
Synonyms: WDR50; CGI-48
Tractability: Small molecule: a structure with a bound ligand is known. PROTAC: UniProt records ubiquitination sites on it; ubiquitination databases record sites on it; its protein half-life has been measured.
Gene: Protein-coding gene on chromosome 17 (51,260,491 to 51,297,936, forward strand). Ensembl gene ENSG00000011260.
Subcellular location: Nucleus, nucleolus
Subcellular location (Human Protein Atlas): Nucleoli; Nucleoli rim; Nuclear membrane; Nucleoplasm
Pathways (Reactome):
Metabolism of RNA: Major pathway of rRNA processing in the nucleolus and cytosol; rRNA modification in the nucleus and cytosol
Gene Ontology:
Molecular function: protein binding; RNA binding
Biological process: ribosomal small subunit biogenesis; maturation of SSU-rRNA; rRNA processing
Cellular component: nucleolus; nucleus; small-subunit processome; nucleoplasm; Pwp2p-containing subcomplex of 90S preribosome
Genetic constraint (gnomAD): Loss-of-function variants: 31 observed, 49.95 expected, observed/expected ratio (o/e) 0.62, 90% interval 0.47 to 0.84. The upper end of that interval is the gene's LOEUF score, 0.84, which puts it in group 3 of 6, group 1 being the genes least tolerant of losing a copy. Missense variants: 690 observed, 649.39 expected, observed/expected ratio (o/e) 1.06, 90% interval 1 to 1.13. Synonymous variants: 269 observed, 235.02 expected, observed/expected ratio (o/e) 1.14, 90% interval 1.03 to 1.27.
Homologues: Orthologues: chimpanzee UTP18 (99% identical), macaque UTP18 (97% identical), pig UTP18 (89% identical), dog UTP18 (88% identical), rabbit UTP18 (88% identical), guinea pig UTP18 (83% identical), rat Utp18 (81% identical), mouse Utp18 (80% identical), tropical clawed frog utp18 (49% identical).
Diseases named in the same sentence as UTP18 in open-access papers:
UTP18 is named in the same sentence as 8 diseases in open-access papers, as found by Europe PMC text mining. Sharing a sentence is not in itself a finding about the gene and the disease. The quoted sentences say what the papers report.
neuroblastoma (2 papers, 2017 to 2022). Neuroblastoma (NB) is the most common solid, extracranial childhood tumor. "The over-expression of UTP18 in neuroblastoma promotes the expression of VEGF, Bcl-2, HIF1α, and c-MYC, improves the adaptability of tumor cells to environmental stress, and reduces the death of neuroblastoma cells after exposure to hydrogen peroxide, hypoxia or glucose deprivation." (PMID 35265610, 2022).
adenoma (1 paper, 2024). A neoplasm arising from the epithelium. "Similarly, an increased cytoplasmic‐to‐nuclear ratio of UTP18 has been observed during normal‐adenoma‐carcinoma progression in colorectal tissues." (PMID 38757623, 2024).
cancer (3 papers, 2017 to 2024). A tumor composed of atypical neoplastic, often pleomorphic cells that invade other tissues. "In the end, CCT6A, UTP18, YRDC, RRP12, RFT1, NLE1, and DDOST were essential genes across pan-cancer including COAD cells." (PMID 31867042, 2019). "Dependency score analysis by DepMap showed that ACTG1 and RHOQ were less essential across pan-cancer cells including COAD cell lines, and CCT6A, UTP18, YRDC, RRP12, RFT1, NLE1, as well as DDOST were essential across pan-cancer cells including most of COAD cell lines." (PMID 31867042, 2019). "In addition, CCT6A, UTP18, YRDC, RRP12, RFT1, NLE1, as well as DDOST were essential genes across pan-cancer including COAD cells, and ACTG1 and RHOQ were less essential genes in cancer cells." (PMID 31867042, 2019).
UTP18 also shares sentences with these, for which no sentence is quoted: tumor (3 papers); breast carcinoma (1); colon cancer (1); infection (1); migraine (1).